TYMS (thymidylate synthetase)
Diseases named in the same sentence as TYMS in open-access papers (continued):
Sharing a sentence is not in itself a finding about the gene and the disease.
lymphoma (5 papers, 2012 to 2025). A malignant (clonal) proliferation of B- lymphocytes or T- lymphocytes which involves the lymph nodes, bone marrow and/or extranodal sites. "We observed that overexpression of TYMS was associated with enhanced widespread involvement in lymphomas and histiocytic sarcomas in hTS/Ink4a/Arf−/− as compared to Ink4a/Arf−/− mice." (PMID 37106126, 2023). "Similar to previous reports, Ink4a/Arf+/− mice developed lymphoma and fibrosarcoma and we found that overexpression of TYMS resulted in a higher incidence of these tumors in hTS/Ink4a/Arf+/- mice." (PMID 37106126, 2023). "Spleens infiltrated with lymphoma or histiocytic sarcoma (n = 5) showed higher TYMS expression levels as compared to normal spleens (n = 1) from hTS/Ink4a/Arf−/− mice." (PMID 37106126, 2023). "Since we showed enhancement of hematopoietic neoplasia following overexpression of TYMS in Ink4a/Arf−/− mice we investigated whether human lymphomas also expressed high TYMS levels." (PMID 37106126, 2023). "Therefore, Ink4a/Arf null mice (that are prone to develop soft tissue sarcoma) exposed to an oncogenic stimulus such as TYMS overexpression, develop not only several subtypes of soft tissue sarcoma but also lymphomas and histiocytic sarcomas in the same animal." (PMID 37106126, 2023). "Therefore, TYMS overexpression in an Ink4a/Arf null background increases the incidence of histiocytic sarcoma and can increase tumor infiltration of both histiocytic sarcomas and lymphomas compared to Ink4a/Arf−/− control." (PMID 37106126, 2023). "The difference in the expression patterns of genes between the healthy and DLBCL samples in the canine dataset highlighted important lymphoma-specific up-regulated genes including DHFR, MS4A1, MYC, POLA1, POLE, RRM1, TOP2A and TYMS." (PMID 24023754, 2013). "Overexpression of TYMS in Ink4a/Arf−/− mice did not increase the incidence of lymphoma, however we observed that similarly to histiocytic sarcomas, lymphomas were more aggressive with extensive multiorgan infiltration." (PMID 37106126, 2023). "No TYMS expression was detected in normal spleen or in a spleen affected with lymphoma from Ink4a/Arf−/− mice." (PMID 37106126, 2023).
metastatic disease (4 papers, 2015 to 2023). "We finally show that HSP90 and Src antagonism are highly effective in suppressing TYMS expression and primary tumor growth, dissemination in circulation, and metastatic tumor formation of the HCT116/R cells." (PMID 26416450, 2015).
mucositis (4 papers, 2016 to 2022). Mucositis is inflammation and damage of the mucous membranes lining the mouth and other parts of the gastrointestinal (GI) tract. "A meta-analysis of four studies showed that TYMS (rs34743033) was marginally associated with a reduced risk of mucositis under the dominant model (OR = 0.66, 95% CI = 0.47–0.94)." (PMID 34744734, 2021). "In contrast, MTHFR (rs1801133), MTHFR (rs1801131), and TYMS (rs34743033) were associated with a reduced risk of G3-4 hepatic toxicity, renal toxicity, and mucositis, respectively." (PMID 34744734, 2021).
squamous cell carcinoma (4 papers, 2013 to 2023). A carcinoma arising from squamous epithelial cells. "We observed that patients with adenocarcinoma exhibited higher TYMS levels compared to those with squamous cell carcinoma, which was in accordance with the results of the latter study." (PMID 24649266, 2013).
squamous cell carcinomas of the lung (4 papers, 2016 to 2021). "Similar results were found in squamous cell carcinoma of the lung where high expression of TYMS precludes response to pemetrexed." (PMID 27802291, 2016). "Elevated expression of TYMS is believed to be one reason for the low efficacy of pemetrexed in SCLC; similarly, squamous cell carcinomas of the lung express higher amounts of TYMS, which show poor response rates to pemetrexed-based therapies." (PMID 27064343, 2016).
colorectal adenocarcinoma (3 papers, 2005 to 2021). The most common type of colorectal carcinoma. "We found significantly higher expression of thymidylate synthase (TYMS) and GSTP1 in mucinous colorectal adenocarcinomas than in equivalent-stage nonmucinous tumours." (PMID 15655543, 2005).
diffuse large B-cell lymphoma (3 papers, 2023 to 2024). "In addition, diffuse large B-cell lymphoma (DLBCL) samples from the same dataset were included in the group of tumors with high TYMS expression." (PMID 37106126, 2023).
esophageal squamous cell carcinoma (3 papers, 2014 to 2023). Esophageal squamous cell carcinoma (ESCC) is a type of esophageal carcinoma (EC) that can affect any part of the esophagus, but is usually located in the upper or middle third. "However, to the best of our knowledge no study has been conducted using ERCC1, TYMS, TUBB3, RRM1 and TOP2A simultaneously in esophageal squamous cell carcinoma (ESCC)." (PMID 24926347, 2014).
folate deficiency (3 papers, 2017 to 2021). A nutritional condition produced by a deficiency of FOLIC ACID in the diet. "In the present study, we further discovered that shMTHFR promoted the expression and translocation of SHMT1/DHFR/TYMS complex in the nucleus during folate deficiency." (PMID 34502300, 2021). "In the present study, folate depletion resulted in a significant reduction in SHMT/DHFR/TYMS, and shMTHFR-promoted nuclei SHMT1/DHFR/TYMS protein expression and translocation, in particular, under folate deficiency." (PMID 34502300, 2021). "The most sensitive pathways to folate deficiency are the MTCH and MTD activities of MTHFD1, MTHFR, MTR, DNMT, DHFR, and TYMS (row showing absolute flux differences between folate levels)." (PMID 28400561, 2017).
Hand-foot syndrome (3 papers, 2019 to 2022). "The altered ENOSF1/TYMS ratio could also be the underlying basis of the severe hand-foot syndrome that is observed in a subset of cancer-affected individuals treated with 5-fluorouracil and related cancer drugs." (PMID 35931051, 2022). "This “C-A-ins” haplotype (rs699517-rs2790-rs151264360) is associated with both reduced TYMS and increased ENOSF1 expression as well as with severe hand-foot syndrome." (PMID 35931051, 2022). "Several recent studies have suggested that the TYMS TSER germline polymorphism may be useful to prevent toxicity, such as hand-foot syndrome and other ADR types, including haematological and gastrointestinal ones." (PMID 32899374, 2020).
Mucinous tumors (3 papers, 2005 to 2025). "The finding of overexpression of TYMS in mucinous tumours in our study offers a possible explanation as to why patients with these tumours tend to do worse." (PMID 15655543, 2005). "Furthermore, TYMS expression was higher in poorly differentiated tumors from patients in group 1 compared to well/moderately differentiated or mucinous tumors (p = 0.010)." (PMID 40357991, 2025). "Among patients treated with 5-FU, those with mucinous tumours had significantly higher TYMS expression (mean 20.8 vs 7.4 for patients with nonmucinous tumours who received 5-FU, P=0.014)." (PMID 15655543, 2005). "In conclusion, mucinous tumours significantly overexpressed TYMS and GSTP1 relative to both normal mucosa and to nonmucinous adenocarcinomas." (PMID 15655543, 2005).
Obesity (3 papers, 2020 to 2022). Accumulation of substantial excess body fat. "This study was to examine the capacity of TYMS expression level in CRC cells in response to capecitabine cytotoxicity under obesity-visfatin stimulation and try to find a potential enhancer capacity of resveratrol in anti-CRC progression." (PMID 34947902, 2021). "Several hub genes, such as TOP2A, CENPF, TYMS, AURKA, KIF4A, and KIF20A, are related to the cell cycle and DNA replication, implicating the close relationship between obesity and cancer." (PMID 36232337, 2022).
rectal tumors (3 papers, 2008 to 2025). "ABCC3 expression was significantly lower (p < 0.0001) and TYMS expression significantly higher (p = 0.0006) in rectal tumors subjected to radiotherapy (n = 43) compared to those that were not (n = 36)." (PMID 40357991, 2025).
renal cell carcinoma (3 papers, 2011 to 2015). "Studies analyzing TYMS expression in cohorts of clinical samples reported a link between TYMS up-regulation and adverse clinical behavior in many solid tumor types including lung, breast, gastric, colorectal, and renal cell cancers." (PMID 25762627, 2015). "Overexpression of miR-215 reduced the expression of TYMS and MDM2 in renal cell carcinoma." (PMID 26317904, 2015).
rheumatoid arthritis (3 papers, 2014 to 2020). A chronic, systemic autoimmune disorder characterized by inflammation in the synovial membranes and articular surfaces. "It has been reported that patients with rheumatoid arthritis and TYMS 3R3R genotype show a weaker response to MTX therapy." (PMID 32344632, 2020). "Therapeutic outcome of rheumatoid arthritis (RA) patients treated with methotrexate (MTX) can be modulated by thymidylate synthase (TS) levels, which may be altered by genetic polymorphisms in TS gene (TYMS)." (PMID 25279663, 2014).
anemia (2 papers, 2019 to 2020). A reduction in the number of red blood cells, the amount of hemoglobin, and/or the volume of packed red blood cells. "In conclusion, an association was found between VNTR and TYMS 1494 ins/del polymorphism in TYMS gene and anemia and neurotoxicity, respectively." (PMID 32695278, 2020). "Interestingly, chemotherapeutic agents targeting TYMS, and reducing its expression, have grade 1 anemia as secondary effects, suggesting that deleterious mutations in this gene may produce anemia." (PMID 31266445, 2019).
brain infarction (2 papers, 2024 to 2025). Tissue necrosis in any area of the brain, including the cerebral hemispheres, the cerebellum, and the brain stem. "GART, TYMS, PPAT, and CTPS1 had the strongest association with inflammation, followed by atherosclerosis and cerebral infarction." (PMID 38995420, 2024).
dyskeratosis congenita (2 papers, 2022 to 2023). Dyskeratosis congenita (DC) is a rare ectodermal dysplasia that often presents with the classic triad of nail dysplasia, skin pigmentary changes, and oral leukoplakia associated with a high risk of bone marrow failure (BMF) and cancer. "The variant was confirmed to be homozygous in one affected and heterozygous in the parents who did not have any evidence of dyskeratosis congenita, a condition that has recently been linked to digenic inheritance involving TYMS." (PMID 38098057, 2023). "A digenic inheritance pattern of variants occurring at the TYMS-ENOSF1 locus and segregating from parents to proband exert a post-transcriptional epistatic effect in causing severe thymidylate synthase deficiency and disease features of dyskeratosis congenita." (PMID 35931051, 2022).
liposarcoma (2 papers, 2021 to 2023). A usually painless malignant tumor that arises from adipose tissue. "Besides, our studies also found that TYMS and RRM2 mRNA expression was higher in liposarcoma than normal adipose tissues and that TYMS overexpression was associated with poor prognosis in liposarcoma patients." (PMID 34868934, 2021). "In this study, the knockdown of TYMS promoted apoptosis and reduced cell migration and invasion of retroperitoneal liposarcoma cells." (PMID 37373974, 2023). "While the previous study revealed TYMS downregulation inhibited STAT3 phosphorylation in liposarcoma cell and RRM2 downregulation inhibited the AKT signaling pathway." (PMID 34868934, 2021). "Our previous studies have indicated that TYMS and RRM2 are key genes in liposarcoma development and progression." (PMID 34868934, 2021). "Western blotting verified that Apatinib downregulated the TYMS/STAT3/PD-L1 pathway and inhibited liposarcoma proliferation by suppressing the RRM2/PI3K/AKT/mTOR pathway." (PMID 34868934, 2021). "Apatinib may inhibit liposarcoma cell proliferation through RRM2/PI3K/AKT/mTOR signaling pathway, and down-regulate PD-L1 through TYMS/STAT3 signaling pathway." (PMID 34868934, 2021). "Apatinib might inhibit liposarcoma cell proliferation through the RRM2/PI3K/AKT/mTOR signaling pathway and downregulate PD-L1 via the TYMS/STAT3 signaling pathway." (PMID 34868934, 2021).
lymph node metastasis (2 papers, 2020 to 2022). "Moreover, expression of TYMS in tumors with lymph node metastasis (N1) was higher than in tumors without (N0)." (PMID 35528004, 2022).
malignant uterine tumors (2 papers, 2022 to 2023). "Most importantly, TYMS, TK1, miR-26b-5p, and Sp1 panel should be further investigated as biomarkers of pathogenesis, prognosis, and differentiation of uLMS from other benign and malignant uterine tumors." (PMID 37373974, 2023).
medulloblastoma (2 papers, 2015 to 2018). A malignant, invasive embryonal neoplasm arising from the cerebellum. "The Daoy medulloblastoma cells showed higher relative expression of the RFC1, DHFR and TYMS genes, whereas the expression of these genes was very weak in the MBL-02 medulloblastoma cells." (PMID 25739012, 2015).
mucinous adenocarcinoma (2 papers, 2005 to 2018). An invasive adenocarcinoma composed of malignant glandular cells which contain intracytoplasmic mucin. "Patients suffering mucinous adenocarcinoma and receiving 5-FU show a diminished clinical response compared to those with nonmucinous tumors; this discrepancy likely results from a significant higher expression of TYMS gene encoding TS." (PMID 29416702, 2018). "Perhaps decreased response to 5-FU due to overexpression of TYMS contributes to the relatively poorer prognosis for patients with mucinous adenocarcinoma." (PMID 15655543, 2005). "Longer patient follow-up and standardised treatment will be required to fully explore the role of TYMS and GSTP1 overexpression in mucinous adenocarcinoma." (PMID 15655543, 2005).
myeloma (2 papers, 2021 to 2022). "In the recent study based on scRNA‐seq, STMN1 and TYMS were identified to be related to resistance pathways of myeloma cells." (PMID 35297204, 2022). "Interestingly, this PHF19 high myeloma cell subtype also exhibited high expression of genes involved in cell cycle including HELLS, EZH2, TYMS, ZWINT, and MKI67." (PMID 34857028, 2021). "Interestingly, this PHF19high myeloma cell subpopulation seems to be the cell cycling fraction as they also exhibited high expression of genes involved in cell cycling including HELLS, EZH2, TYMS, ZWINT, and MKI67." (PMID 34857028, 2021).
neuroblastoma (2 papers, 2006 to 2024). Neuroblastoma (NB) is the most common solid, extracranial childhood tumor. "When maternal choline consumption was below the 25th percentile, offspring carrying the G allele of rs1738575 (MTHFD1L) had an increased risk of neuroblastoma, whereas those with the A allele in SNP rs9966612 (TYMS) had a lower risk of developing neuroblastoma." (PMID 38613027, 2024).
neutropenia (2 papers, 2018). A decrease in the number of neutrophils found in the blood. "In our study the 3R3R genotype of 28bp repeat VNTR variant in TYMS gene (rs34743033) was responsible for elevated risk of severe neutropenia." (PMID 29507678, 2018). "In our group two independent predictors of severe neutropenia, variants in TYMS and DPYD genes, belong to 5-fluorouracil pathway." (PMID 29507678, 2018).
oral cancer (2 papers, 2023). "The thymidylate synthetase inhibitor 5-FU is widely used in the treatment of various cancers, including oral cancer, as it interrupts DNA synthesis, leading to cell death by apoptosis." (PMID 37049698, 2023).
osteonecrosis (2 papers, 2016 to 2018). A none disease characterized by death of bone tissue due to a lack of blood supply. "This study aimed to investigate the relationship between vitamin D receptor fok1 (VDR fok1) and thymidylate synthase (TYMS) gene polymorphisms with the glucocorticoid (GC) induced osteonecrosis (ON) in Egyptian pediatric ALL patients." (PMID 30533396, 2018). "Among various SNPs, only polymorphisms in the VDR and TYMS were independent predictors for osteonecrosis." (PMID 30533396, 2018). "Genetic polymorphisms in several genes including SERPINE1, VDR, CYP3A4, TYMS, PAI 1, and ACP 1 were documented to be associated with osteonecrosis." (PMID 30533396, 2018). "Another important enzyme, TYMS, that converts 2,10-CH2-THF to DHF, was found to be associated with relapse, stomatitis or osteonecrosis in children with ALL." (PMID 27618021, 2016). "VDR fok1 and TYMS tandem repeats in cases with osteonecrosis vs. controls (N = 102)." (PMID 30533396, 2018).
retinoblastoma (2 papers, 2024). A malignant tumor that originates in the nuclear layer of the retina. "Finally, another feature of retinoblastoma is that TYMS mRNA levels are high, suggesting that these tumor cells rely on dUMP, and therefore on UMP for the synthesis of dTTP." (PMID 38332874, 2024).
sarcoma (2 papers, 2015 to 2022). A usually aggressive malignant neoplasm of the soft tissue or bone. "In subcutaneously transplanted sarcoma, TYMS is expressed in a circadian manner." (PMID 35903686, 2022). "Moreover, TYMS was expressed in a circadian manner in subcutaneously transplanted sarcoma, which further corroborates our observations in synchronized CRC cells, indicating fluctuating activity of pyrimidine-metabolizing enzymes." (PMID 35903686, 2022). "Downregulation of TYMS by both ibandronate and simvastatin in some of the tested cell lines from our own study could explain a previous study that demonstrated the effect of mevalonate pathway inhibitors on DNA damage response in human sarcoma cells." (PMID 25978957, 2015).
Sepsis (2 papers, 2022 to 2024). Sepsis is defined as life-threatening organ dysfunction caused by a dysregulated host response to infection. "In comparison to sepsis patients, only TYMS demonstrated significant changes in expression among these characteristic genes in ARDS patients, indicating a remarkable upregulation." (PMID 38558817, 2024). "qRT-PCR and WB detection showed that TYMS was highly expressed in EPCs of sepsis patients compared with the Healthy group." (PMID 35082972, 2022). "Our study showed that, compared with the Healthy group, the expressions of TYMS were high in the Sepsis group." (PMID 35082972, 2022). "Compared with Healthy group, lncRNA IGF2-AS, HMGA1, and TYMS were highly expressed in Sepsis group." (PMID 35082972, 2022). "This is also the first time that we reported the studies on RRM2, TK1, and TYMS in sepsis." (PMID 35082972, 2022).
soft tissue sarcoma (2 papers, 2022 to 2023). A malignant neoplasm arising from muscle tissue, adipose tissue, blood vessels, fibrous tissue, or other supportive tissues excluding the bones. "Since we observed that TYMS overexpression in Ink4a/Arf−/− mice increased the incidence of soft tissue sarcoma and significantly decreased hTS/Ink4a/Arf−/− survival compared to Ink4a/Arf−/− mice, we analyzed TYMS levels in human soft tissue sarcoma." (PMID 37106126, 2023). "To further study the effect of TYMS overexpression in mice that developed soft tissue sarcoma, we compared survival of hTS/Ink4a/Arf−/− mice diagnosed with soft tissue sarcoma including fibrosarcoma vs Ink4a/Arf−/− mice that only developed fibrosarcoma." (PMID 37106126, 2023). "Data from The Cancer Genome Atlas (TCGA) reveled that soft tissue sarcoma was among the group of tumors with highest levels of TYMS and TYMS transcripts were 3-fold more abundant in soft tissue sarcoma (n = 191) than in normal tissues (n = 2)." (PMID 37106126, 2023).
spina bifida (2 papers, 2009 to 2014). A congenital neural tube defect in which vertebrae are not fully formed. "Three of the five TYMS SNPs (rs284179, rs1001761, and rs502396) investigated here showed elevated risks for spina bifida for both heterozygote or homozygote individuals." (PMID 19493349, 2009). "We observed evidence of a nonrandom haplotype association with TYMS for spina bifida and conotruncal heart defects among nonHispanic whites." (PMID 19493349, 2009). "Haplotype reconstruction showed statistical evidence of nonrandom associations with TYMS, MTHFR, BHMT and MTR for spina bifida." (PMID 19493349, 2009). "Blocks for TYMS, MTHFR, BHMT, and MTR showed some evidence of nonrandom effects for spina bifida." (PMID 19493349, 2009).